RGS4 (regulator of G protein signaling 4)
Description:
Inhibits signal transduction by increasing the GTPase activity of G protein alpha subunits thereby driving them into their inactive GDP-bound form. Activity on G(z)-alpha is inhibited by phosphorylation of the G protein. Activity on G(z)-alpha and G(i)- alpha-1 is inhibited by palmitoylation of the G protein.
Synonyms: RGP4; SCZD9
Tractability: Small molecule: it belongs to a druggable protein family. Antibody: its Gene Ontology location is reachable by antibodies, with high confidence. PROTAC: a small molecule that binds it is known.
Gene: Protein-coding gene on chromosome 1 (163,068,775 to 163,076,802, forward strand). Ensembl gene ENSG00000117152.
Subcellular location (Human Protein Atlas): Cytosol
Pathways (Reactome):
Signal Transduction: G alpha (i) signalling events; G alpha (q) signalling events; G alpha (z) signalling events
Gene Ontology:
Molecular function: calmodulin binding; GTPase activator activity; GTPase activity; G-protein alpha-subunit binding; protein kinase binding
Biological process: G protein-coupled receptor signaling pathway; negative regulation of G protein-coupled receptor signaling pathway; regulation of G protein-coupled receptor signaling pathway; dorsal root ganglion development; negative regulation of cell growth involved in cardiac muscle cell development; negative regulation of dopamine receptor signaling pathway; negative regulation of glycine import across plasma membrane; negative regulation of potassium ion transmembrane transport; positive regulation of excitatory postsynaptic potential; positive regulation of heart rate; regulation of actin filament organization; regulation of calcium ion transport; regulation of potassium ion transmembrane transport; response to amphetamine; response to cocaine; response to ethanol
Cellular component: cytoplasm; nucleus; cytoplasmic side of plasma membrane; plasma membrane; protein-containing complex
Genetic constraint (gnomAD): Loss-of-function variants: 15 observed, 19.25 expected, observed/expected ratio (o/e) 0.78, 90% interval 0.52 to 1.2. The upper end of that interval is the gene's LOEUF score, 1.2, which puts it in group 5 of 6, group 1 being the genes least tolerant of losing a copy. Missense variants: 231 observed, 242.89 expected, observed/expected ratio (o/e) 0.95, 90% interval 0.85 to 1.06. Synonymous variants: 92 observed, 88.78 expected, observed/expected ratio (o/e) 1.04, 90% interval 0.88 to 1.23.
Homologues: Orthologues: chimpanzee RGS4 (100% identical), macaque RGS4 (100% identical), rat Rgs4 (97% identical), mouse Rgs4 (96% identical), pig RGS4 (96% identical), rabbit RGS4 (96% identical), dog RGS4 (95% identical), guinea pig RGS4 (94% identical), tropical clawed frog rgs4 (67% identical), zebrafish rgs4 (48% identical). Paralogues in human: RGS3 (48% identical), RGS5 (45% identical), RGS16 (44% identical), RGS8 (42% identical), RGS1 (39% identical), RGS18 (39% identical), RGS2 (39% identical), RGS12 (34% identical), RGS21 (34% identical), RGS20 (34% identical), RGS13 (33% identical), RGS19 (31% identical), and 11 more.
Diseases named in the same sentence as RGS4 in open-access papers:
RGS4 is named in the same sentence as 96 diseases in open-access papers, as found by Europe PMC text mining. Sharing a sentence is not in itself a finding about the gene and the disease. The quoted sentences say what the papers report.
schizophrenia (44 papers, 2005 to 2025). A major psychotic disorder characterized by abnormalities in the perception or expression of reality. "The study suggests NAC as a promising therapeutic option for RGS4 deficiency-related schizophrenia due to its specific action on the xCT transporter." (PMID 41020832, 2025). "RGS4 is known to be a schizophrenia susceptibility gene and is downregulated in the cortex of schizophrenia patients." (PMID 36437991, 2022). "Rgs4 is considered a strong candidate susceptibility gene for schizophrenia and a strong decrease of its mRNA and proteins levels have been described in postmortem samples of schizophrenia patients." (PMID 34172795, 2021). "Here, we conducted an updated meta-analysis to detect the association between RGS4 gene polymorphisms and the risk of schizophrenia." (PMID 34871224, 2021). "The negative regulator of G-protein signalling 4 (Rgs4) is linked to several neurologic diseases, e.g. schizophrenia, addiction, seizure and pain perception." (PMID 32779957, 2021). "First, in the present study, the East Asian population contributed to the association between the RGS4 gene and the risk of schizophrenia; however, the sample size was relatively small, and the power was low." (PMID 34871224, 2021). "RGS4 dysfunction has been linked to many diseases, including hypertension, schizophrenia, and Parkinson’s disease." (PMID 33067534, 2020). "Amongst the schizophrenia-susceptibility genes with the most prominent TTTPs were those with established synaptic functions, including Rgs4, Snap25, Kalrn, Htr2a and Nrg1." (PMID 28893375, 2017). "The Regulator of G protein signaling 4 (RGS4) gene is associated with susceptibility to schizophrenia (SCZ)." (PMID 26973546, 2016). "The Regulator of G protein signaling 4 (RGS4) gene is a candidate susceptibility gene for schizophrenia (SCZ)." (PMID 26973546, 2016). "Genes previously showing strong genetic evidence implicated in schizophrenia identified in this study include: regulator of G-protein signaling 4 (RGS4); discoidin domain receptor family, member 1(DDR1); and the selenium binding protein 1(SELENBP1)." (PMID 26818902, 2016). "Reduced expression of the “regulator of g-protein signaling” protein RGS4 has been implicated in schizophrenia." (PMID 25505409, 2014). "The Rgs4 gene encodes the Regulator of G-Protein Signalling 4 (RGS4) protein, an inhibitor of signalling from G-protein coupled receptors, and dysregulation of Rgs4 is linked to disease states such as schizophrenia and cardiomyopathy." (PMID 22970249, 2012). "For instance, certain RGS4 polymorphisms appear to contribute to structural alterations in brain areas previously associated with schizophrenia." (PMID 20119529, 2009). "Initially evidence for linkage with schizophrenia was reported near RGS4 at 1q21-22 and several association studies also suggested modest associations for certain RGS4 gene variants." (PMID 18834502, 2008). "NAC alleviates xCT system dysfunction caused by RGS4 deficiency by preserving cysteine and glutamate exchange, offering a targeted method to restore glutamatergic signaling in the prefrontal cortex for this schizophrenia subtype." (PMID 41020832, 2025). "Rgs4 regulates G protein signaling and might be a schizophrenia susceptibility gene; Rgs4 deficit in prefrontal cortex contributes to the behaviors related to schizophrenia." (PMID 35781563, 2022). "Subgroup association of RGS4 polymorphisms with schizophrenia." (PMID 34871224, 2021). "Pooled association of RGS4 polymorphisms with schizophrenia." (PMID 34871224, 2021). "Meanwhile, polymorphisms of the RGS4 gene have been identified in schizophrenia patients." (PMID 23977258, 2013). "Rgs4 is expressed predominantly in neural and vascular cells, and the Rgs4 locus has been linked to disease states relating to both types of cell, notably in schizophrenia." (PMID 22970249, 2012).
schizophrenia (continued). "Our analysis has found that RGS4 variants exhibit some tentative signals for association with endophenotypes that might be relevant to the pathogenesis of schizophrenia." (PMID 18834502, 2008). "Indeed RGS4 itself was the second-most highly down-regulated gene in our entire meta-analysis and has previously been associated with diseases ranging from AD and HD, to schizophrenia and depression." (PMID 25187168, 2014). "Studies using cDNA microarrays have consistently shown decreased RGS4 expression in the prefrontal cortex of subjects with schizophrenia, suggesting implications for CBD in anxiety and mental disorder therapies." (PMID 40335839, 2025). "RGS4 expression deficit in the prefrontal cortex was also found to contribute to behaviors related to schizophrenia in mice." (PMID 39202417, 2024). "In the brain tissues of schizophrenia patients, it is known that the expression of RGS4 is decreased." (PMID 39202417, 2024). "A few studies have detected the function of miRNAs in the development of schizophrenia via their binding with the 3′UTR of the RGS4 gene." (PMID 39202417, 2024). "Microarray and genomic analysis studies show that transcript level of RGS4 in the PFC are decreased in a diagnosis-specific manner in schizophrenia patients." (PMID 35781563, 2022). "We found that RGS4 and RANGAP1 both had multiple significant meta path types indicating their potential associations and mechanisms associated with schizophrenia." (PMID 35412455, 2022). "In the present study we investigated the possible association of polymorphisms from five candidate genes RGS4, SLC6A3, PIP4K2A, BDNF, PI4KA with response to antipsychotic in variably ill schizophrenia patients." (PMID 25025909, 2014). "In present study, MDR results suggested interaction between RGS4_rs2842026-SLC6A3_rs2975226 in schizophrenia patients of LSG and between BDNF_rs7103411-BDNF_rs1491851-SLC6A3_rs40184 in severely ill patients for their inadequate treatment response." (PMID 25025909, 2014). "The active molecules from these plants were docked with RGS-4 protein (regulator for G protein signaling-4) considered to be responsible for schizophrenia." (PMID 24864161, 2014). "Microarray and genomic analyses showed decreased levels of RGS4 in the prefrontal cortex in patients with schizophrenia." (PMID 23977258, 2013). "It has been previously shown that RGS4 expression is decreased across 3 cortical areas (including the PFC) of subjects with schizophrenia." (PMID 23840971, 2013). "Rgs4 dysfunction is thought to be related to disease states such as schizophrenia and heart hypertrophy." (PMID 22970249, 2012). "Our analysis showed that both disorders share three common DETs, namely Rgs4, Ppp1r1b and Chgb, whose expression is downregulated in humans with Huntington's disease or schizophrenia." (PMID 19799774, 2009). "Decreased STG expression of the regulator of G-protein signalling 4 (RGS4) mRNA in schizophrenia supports RGS4 as a potential genetic and functional biological marker of schizophrenia." (PMID 19333451, 2009). "Regulator of G-protein signaling 4 (RGS4) is a schizophrenia candidate gene that was identified by Mirnics and colleagues and has subsequently been reported in linkage and convergent functional genomics studies." (PMID 18445270, 2008). "The expression of two previously reported putative genes for schizophrenia, RGS4 and RIMS2 was also measured." (PMID 18445270, 2008). "This down-regulation of RGS4 expression in the STG is in accordance with the decreased expression previously reported in the PFC, motor and visual cortices in schizophrenia further establishing RGS4 as a schizophrenia candidate gene." (PMID 18445270, 2008). "With this background, in the present study, we investigated 53 polymorphisms from five genes (RGS4, SLC6A3, PIP4K2A, BDNF and PI4KA) in 423 south Indian schizophrenia cases segregated into low and high severity of illness to assess their influence on antipsychotic response." (PMID 25025909, 2014).
schizophrenia (continued). "Genetic studies indicate RGS4 as a vulnerability factor for schizophrenia." (PMID 23977258, 2013). "Although the causes of schizophrenia are not yet understood, one major theory involves dysregulation of dopamine signalling, so it is interesting that RGS4 protein is capable of inhibiting signal transduction from the D2 dopamine receptor." (PMID 22970249, 2012). "Moreover, DTNBP1 and RGS4 have been reported to be differentially expressed in postmortem brain samples of individuals with schizophrenia." (PMID 16033310, 2005). "The detection of simultaneous alterations of presynaptic genes and RGS4 is supportive of the synaptic-neurodevelopmental model of schizophrenia, which suggests that these influences may affect postnatal synapse formation and pruning, which eventually leads to the disorder." (PMID 22558445, 2012). "Importantly, hypoxia and ischaemia have also been associated with schizophrenia, and as such HIF regulation of Rgs4 transcription in specific neural cell types may provide a molecular mechanism linking disrupted oxygen supply to schizophrenia." (PMID 22970249, 2012). "A plausible hypothesis to explain the inconsistencies in these studies is that RGS4 variants may modulate endophenotypes associated with schizophrenia rather than risk of disease itself." (PMID 18834502, 2008). "Depending on the population mix and the importance that these endophenotypes may play in the disease process, some case-control studies of schizophrenia may show subtle effects with RGS4 variants, while others may show none." (PMID 18834502, 2008). "RGS4-1, the longest RGS4 isoform, was reported to be specifically decreased in the DLPFC of schizophrenia patients." (PMID 39202417, 2024). "The docking of RGS-4 protein with the combinations of reserpine, withanolide, and asiaticoside from Rauvolfia serpentina, Withania somnifera, and Mandukparni, respectively, showed that such combination therapy could be helpful in the management of schizophrenia." (PMID 24864161, 2014). "Further research into Rgs4 regulation by hypoxia and HIF may result in better understanding of disease states such as schizophrenia, and also shed light on the other roles of HIF yet to be discovered." (PMID 22970249, 2012). "A possible explanation of the discrepancies is that RGS4 variants might modulate endophenotypes (measurable components expressed as quantitative traits along the pathway to development of the full-blown disease) associated with schizophrenia rather than risk of disease itself." (PMID 20119529, 2009).
breast carcinoma (15 papers, 2010 to 2024). "RGS4 expression suppresses breast cancer migration, invasion, and proliferation, and RGS4 reduces the risk of bladder cancer with an increasing number of variant alleles." (PMID 34748583, 2021). "Studies have shown loss of RGS4 in multiple cancer types, including non-small cell lung cancer, melanoma, and breast cancer." (PMID 34370741, 2021). "However, some studies have reported that increased RGS4 protein significantly inhibits cell migration and invasion in breast cancer and loss of RGS4 is associated with poor prognosis in pediatric nephroblastoma." (PMID 38693916, 2024). "Moreover, RGS4 had been implicated in the enhancement of cell viability or invasiveness in lung cancer, gliomas, ovarian cancer, colorectal cancer and breast cancer." (PMID 39153211, 2024). "RGS4 may inhibit the migration and invasion of breast cancer cells via down-regulating the metastasis-associated Gi-coupled receptors (PAR1 and CXCR4) signal transduction." (PMID 29108247, 2017). "RGS4 functions in breast cancer cells through regulating its classical GAP activity, whereas RGS16 and RGS6 participate in the negative regulation of breast cancer cells in a GAP-independent manner." (PMID 37118788, 2023). "This protein is also significantly expressed in normal breast epithelial cells, and silencing of RGS4 in breast cancer cells enhances the invasive ability of cancer cells." (PMID 37924113, 2023). "In this way, the genes selected for ChIP analysis were: PADI3, a tumour suppressor in CRC, ZDHHC2, a suppressor of metastasis in hepatocellular carcinoma and RGS4, which inhibits the growth of human breast carcinoma cells." (PMID 33801071, 2021). "Previous studies indicated that RGS4 notably inhibited invasion and migration of breast cancer cells by its GAP-mediated activity." (PMID 29108247, 2017). "On the other hand, in breast cancer cells, RGS4 suppresses Ras-related C3 botulinum toxin substrate 1-dependent lamellipodia formation." (PMID 27105500, 2016). "For examples, increased expression of RGS4 mRNA inhibited breast cancer cell migration and invasion." (PMID 26910917, 2016). "Interestingly, the overexpression of RGS4 remarkably inhibited breast cancer cell growth, which was reversed by a pharmacological inhibitor of RGS4." (PMID 34199813, 2021). "For example, some RGS proteins including RGS4, RGS16, RGS2, RGS6 and RGS17 negatively regulate the progression of breast cancer, whereas RGS20 protein exerts the positive effects on potentiating the carcinogenesis of breast cancer." (PMID 37118788, 2023). "RGS2, RGS4 and RGS6 repress cell growth, whose expression is decreased in breast cancer cells, compared to the normal cells." (PMID 37118788, 2023). "Pristimerin was reported to inhibit migration and invasion via targeting G protein signaling 4 (RGS4) in breast cancer MDA-MB-231 cells and HER2 in human breast carcinoma SKBR3 cells." (PMID 31354475, 2019). "Both of RGS4 and PTGS2 have been previously reported to involve in breast cancer cell proliferation and invasion." (PMID 26910917, 2016). "In contrast, the expression patterns of SNX, HTR2B, RGS4, and LYN were not homogeneous and differed among the breast cancer subtypes." (PMID 39267843, 2024).
glioma (10 papers, 2010 to 2024). A benign or malignant brain and spinal cord tumor that arises from glial cells (astrocytes, oligodendrocytes, ependymal cells). "RGS4 has recently been studied as a tumor promoter in glioma cells by acting positively on tumor cell motility, and is reported to be a potent driver of human glioma cell invasiveness." (PMID 32392739, 2020). "Blockade of RGS4 by CCI-779 markedly suppresses glioma cell invasion, suggesting that RGS4 is a key driver of glioblastoma invasiveness." (PMID 27105500, 2016). "RGS4-mediated glioma cell invasion is signaled by mTOR activation." (PMID 27105500, 2016). "However, gene silencing of RGS4 or pharmacological inhibition of its protein reduced cell mobility and invasiveness in glioma cells and in an intracerebral mouse model, respectively." (PMID 27105500, 2016). "LncRNA TRPM2-AS inhibits the cellular processes such as glioma growth and invasion by JNK, c-Jun, and RGS4." (PMID 35854199, 2023). "In the GEPIA database, we found that IKBIP was upregulated in glioma relative to normal tissue, while CCBE1, NRG1, and RGS4 were downregulated in glioma." (PMID 34897031, 2021). "RGS3 and RGS4, which share a similar function with RGS11 in modulating Gαi/o activity are overexpressed in faster migrating glioma cells, which results in greater cell adhesion and chemotaxis." (PMID 27105500, 2016). "We identified 20 GSC-upregulated miRNA-targeted genes associated with significantly reduced 5-year survival in GBM patients, including previously identified glioma-promoting genes HMGA2, MYO1C, RGS4, and several novel targets, such as HPCAL1, IMPDH1, and YWHAG (orange-colored genes)." (PMID 29587824, 2018). "Overexpression of RGS3 and RGS4 leads to the blockade of Gα-dependent chemotaxis in lymphoid cells, whereas increasing expression of either of these RGS proteins increases cell adhesion and chemotaxis in glioma cells." (PMID 27105500, 2016).